LRP1 (LDL receptor related protein 1)
Description:
Endocytic receptor involved in endocytosis and in phagocytosis of apoptotic cells. Required for early embryonic development (By similarity). Involved in cellular lipid homeostasis. Involved in the plasma clearance of chylomicron remnants and activated LRPAP1 (alpha 2-macroglobulin), as well as the local metabolism of complexes between plasminogen activators and their endogenous inhibitors. Acts as an LRPAP1 alpha-2-macroglobulin receptor. Acts as TAU/MAPT receptor and controls the endocytosis of TAU/MAPT as well as its subsequent spread. May modulate cellular events, such as APP metabolism, kinase-dependent intracellular signaling, neuronal calcium signaling as well as neurotransmission. Also acts as a receptor for IGFBP3 to mediate cell growth inhibition. (Microbial infection) Functions as a receptor for Pseudomonas aeruginosa exotoxin A. (Microbial infection) Functions as a receptor for yellow fever virus.
Synonyms: A2MR; APOER; CD91; APR; LRP; LRP1A; IGFBP3R1; IGFBP-3R; DDH3; IGFBP3R; KPA; TGFBR5
Tractability: Antibody: its Gene Ontology location is reachable by antibodies, with high confidence; UniProt places it where antibodies can reach, with medium confidence; UniProt predicts a signal peptide or a membrane-spanning region; the Human Protein Atlas places it where antibodies can reach. PROTAC: ubiquitination databases record sites on it; its protein half-life has been measured. Other modalities: a drug acting on it is in phase 2 or 3 trials.
Gene: Protein-coding gene on chromosome 12 (57,128,483 to 57,213,361, forward strand). Ensembl gene ENSG00000123384.
Subcellular location: Cell membrane (Low-density lipoprotein receptor-related protein 1 85 kDa subunit); Membrane, coated pit; Cell membrane (Low-density lipoprotein receptor-related protein 1 515 kDa subunit); Cytoplasm (Low-density lipoprotein receptor-related protein 1 intracellular domain); Nucleus; Golgi outpost; Cytoplasm, cytoskeleton, microtubule organizing center
Subcellular location (Human Protein Atlas): Plasma membrane; Cytosol; Nucleoli
Pathways (Reactome):
Sensory Perception: Retinoid metabolism and transport
Vesicle-mediated transport: Scavenging of heme from plasma
Gene Ontology:
Molecular function: alpha-2 macroglobulin receptor activity; apolipoprotein binding; cargo receptor activity; clathrin heavy chain binding; protein binding; protein-containing complex binding; RNA binding; virus receptor activity; amyloid-beta binding; apolipoprotein receptor activity; calcium ion binding; heparan sulfate proteoglycan binding; lipoprotein particle receptor binding; low-density lipoprotein particle receptor activity; scavenger receptor activity; signaling receptor activity
Biological process: amyloid-beta clearance by cellular catabolic process; amyloid-beta clearance by transcytosis; phagocytosis; positive regulation of endocytosis; positive regulation of lysosomal protein catabolic process; positive regulation of protein localization to plasma membrane; receptor-mediated endocytosis; regulation of acute inflammatory response; regulation of extracellular matrix organization; amyloid-beta clearance; aorta morphogenesis; apoptotic cell clearance; astrocyte activation involved in immune response; cellular response to amyloid-beta; enzyme-linked receptor protein signaling pathway; lipid metabolic process; lipoprotein transport; lysosomal transport; negative regulation of gene expression; negative regulation of platelet-derived growth factor receptor-beta signaling pathway; negative regulation of SMAD protein signal transduction; negative regulation of smooth muscle cell migration; negative regulation of Wnt signaling pathway; positive regulation of amyloid-beta clearance; positive regulation of cholesterol efflux; and 13 more
Cellular component: basolateral plasma membrane; cytoplasm; cytosol; early endosome; focal adhesion; lysosomal membrane; nucleolus; nucleus; plasma membrane; receptor complex; endocytic vesicle membrane; membrane; plasma membrane protein complex; postsynaptic Golgi apparatus; microtubule organizing center
Genetic constraint (gnomAD): Loss-of-function variants: 51 observed, 544.49 expected, observed/expected ratio (o/e) 0.0937, 90% interval 0.074 to 0.12. The upper end of that interval is the gene's LOEUF score, 0.12, which puts it in group 1 of 6, group 1 being the genes least tolerant of losing a copy. Missense variants: 3,875 observed, 6,540.6 expected, observed/expected ratio (o/e) 0.59, 90% interval 0.58 to 0.61. Synonymous variants: 2,219 observed, 2,544.5 expected, observed/expected ratio (o/e) 0.87, 90% interval 0.84 to 0.9.
Homologues: Orthologues: chimpanzee LRP1 (99% identical), macaque LRP1 (99% identical), dog LRP1 (98% identical), mouse Lrp1 (98% identical), rat Lrp1 (98% identical), guinea pig LRP1 (96% identical), tropical clawed frog lrp1 (82% identical), zebrafish lrp1aa (77% identical), zebrafish lrp1ab (76% identical), Drosophila melanogaster arr (9% identical). Paralogues in human: LRP1B (61% identical), LRP2 (37% identical), LRP4 (12% identical), LRP6 (10% identical), LRP5 (10% identical), LRP8 (7% identical), VLDLR (7% identical), EGF (6% identical), NID1 (6% identical), NID2 (6% identical), LRP3 (4% identical), and 2 more.
Diseases named in the same sentence as LRP1 in open-access papers:
LRP1 is named in the same sentence as 294 diseases in open-access papers, as found by Europe PMC text mining. Sharing a sentence is not in itself a finding about the gene and the disease. The quoted sentences say what the papers report.
Alzheimer disease (92 papers, 2008 to 2026). A progressive, neurodegenerative disease characterized by loss of function and death of nerve cells in several areas of the brain leading to loss of cognitive function such as memory and language. "LRP1 has also been implicated in multiple neurodegenerative diseases, including Alzheimer’s disease, Parkinson’s disease, and Lewy body dementia (28, –, 31)." (PMID 41313001, 2025). "Targeting LRP1 associated with peripheral clearance of beta-amyloid is another promising molecular target for Alzheimer’s disease therapy." (PMID 39456746, 2024). "The LDL-family of receptors and its member LRP1 have classically been associated with a modulation of lipoprotein metabolism and have been studied for example, with reference to Alzheimer’s disease." (PMID 37383546, 2023). "Our proteomics data showed a significant decrease in Alzheimer’s disease-related factors LRP1 and presenilin in RAB35-deficient hippocampus." (PMID 37085665, 2023). "In additional to its role in lipid homeostasis, LRP1 has also been implicated in Alzheimer’s disease, for which metabolic disease and obesity are risk factors." (PMID 35435227, 2022). "Connecting to Alzheimer’s disease, dementia, and amyloidosis hubs include prominent AD-associated proteins such as the low-density lipoprotein receptor-related proteins LRP1, LRP1B, LRP4, and LRP6." (PMID 33946285, 2021). "LRP1, previously implicated in both Alzheimer’s disease and GluA1 trafficking, was also identified by mass spectrometry." (PMID 34720876, 2021). "The deletion of LRP1 in astrocytes caused a negatively influenced cellular uptake of Aβ and degradation involved in Alzheimer’s Disease (AD) progression." (PMID 33679332, 2021). "TPA, alike Lrp1, is implicated in the pathology of neurodegenerative diseases, including Alzheimer’s disease, psychotic disorders like schizophrenia and is recognized for supporting BBB integrity." (PMID 30931303, 2019). "Similar to α2M, there are conflicting reports regarding an association between polymorphisms in LRP1 and the risk of Alzheimer's disease." (PMID 31428227, 2019). "Low density lipoprotein receptor-related protein 1 (LRP1) C766T polymorphism (rs1799986) has been extensively investigated for Alzheimer’s disease (AD) susceptibility." (PMID 28814781, 2017). "Polymorphisms in the LRP1 gene have been associated with increased risk for Alzheimer's disease and LRP1 levels are significantly reduced in AD patients." (PMID 22537779, 2012). "We and others have used mice with targeted deletion of LRP1 receptor associated protein (RAP), which regulates LRP1 maturation, as a means to reduce LRP1 levels in mouse models of Alzheimer's disease." (PMID 22537779, 2012). "The low-density lipoprotein receptor-related protein (LRP1) and its family members have been implicated in the pathogenesis of Alzheimer's disease." (PMID 22537779, 2012). "One significant protein linked to the development of Alzheimer's disease is the low-density lipoprotein receptor-related protein-1 (LRP1), whose dysfunction may contribute to the disease." (PMID 40464180, 2025). "Interestingly, despite this defect, less extracellular β-amyloid peptides and reduced plaque deposition were found in Alzheimer's disease mice that also carry the LRP1 distal NPxY mutation." (PMID 33500241, 2021). "Furthermore, LRP1 was implicated in the pathogenesis of several human diseases including Alzheimer’s disease, breast cancer, and prostate cancer, although it has not been directly studied in diabetes or DKD." (PMID 34572299, 2021). "The observed low hepatic expression of Lrp-1 in SHRs and the subsequent downregulation by high physical activity increases the risk of steatosis and insulin resistance but also that of Alzheimer Disease as brain and hepatic expressed Lrp-1s are part of clearance of misfolded amyloid β oligomers." (PMID 33833685, 2021).
Alzheimer disease (continued). "Current advances in understanding the ischemic etiology of Alzheimer's disease have revealed dysregulation of Alzheimer's disease-associated genes, including secretases, amyloid precursor protein, apoptosis, autophagy, mitophagy, tau protein, α-synuclein, apolipoproteins, LRP1, and RAGE." (PMID 42222332, 2026). "In Alzheimer’s disease, early evidence has shown that LRP1 activation can facilitate the clearance of amyloid-β, which can be induced with formononetin treatment." (PMID 38786045, 2024). "Only an Aβ-producing murine model crossed with Lrp1-/- mice, without a tau protein gene mutation, resulting in the secondary accumulation of tau protein, would be a proper model to evaluate the exact role of LRP1 in the pathology of Alzheimer’s disease." (PMID 39273636, 2024). "Increasing LRP1 levels reduced amyloid β and reversed the behavioural deficits in Alzheimer’s disease." (PMID 37111543, 2023). "Here, the authors report that ANKS1A promotes the LRP1-mediated Aβ clearance in brain endothelium, providing insights into the pathology of Alzheimer’s disease." (PMID 38123547, 2023). "Instead, they have received more attention in the context of Alzheimer’s disease, in particular LRP1 and LRP2 of which Aβ, like tPA, is a ligand." (PMID 36243724, 2022). "Consistently, LRP-1 is involved in the export of Aβ from the brain, while LRPAP1 gene polymorphisms are associated with late-onset Alzheimer’s disease." (PMID 36012423, 2022). "Collectively, our data provide the first demonstration of the participation of syndapin-2 in LRP1-mediated Aβ clearance across BECs, and its role in the accumulation of Aβ within the brain in Alzheimer’s disease and ageing." (PMID 35233527, 2022). "Recent findings from eyes of Alzheimer’s disease patients show a correlation between retinal Aβ accumulation and diminished retinal vascular LRP1 expression." (PMID 33671133, 2021). "Due to its ability to mediate actions of a broad range of ligands, LRP1 participates in the development of multiple degenerative diseases, such as atherosclerosis and Alzheimer's disease." (PMID 34124208, 2021). "Exercise has been shown before to increase the hepatic expression of LRP-1 in a mouse model of Alzheimer Disease." (PMID 33833685, 2021). "The main effects and interaction of LRP1 genotype and disease status focused on the core hubs of frontal‐parietal network across the Alzheimer's disease spectrum." (PMID 34387022, 2021). "More importantly, the diminishment of abluminal LRP1 is closely related to intracranial Aβ accumulation in Alzheimer’s disease, and also to the aggregation of α-synuclein into Lewy bodies in Parkinson’s disease." (PMID 34959306, 2021). "In a mouse model of Alzheimer's disease, treatment with recombinant ligand-binding domain IV of LRP1 by using an in situ arterial brain perfusion technique for 3 months reduced brain Aβ levels." (PMID 34124208, 2021). "It is known that astrocytic LRP1 plays a critical role in brain Aβ clearance involved in Alzheimer’s disease (AD) pathogenesis." (PMID 33519378, 2020). "α2M is found colocalised with the Aβ peptide in the brain in Alzheimer's disease, which supports the idea that the LRP1-mediated clearance of α2M-Aβ complexes is impaired or overwhelmed." (PMID 31428227, 2019). "In order to analyze the net effect of LRP1 on production and clearance of Aβ in vivo, we crossed mice with impaired LRP1 function with a mouse model of Alzheimer’s disease (AD)." (PMID 31004319, 2019). "Dysregulation of LRP1-dependent signaling events contributes to the development of pathophysiologic processes such as Alzheimer’s disease, atherosclerosis, inflammation, and coagulation." (PMID 28589128, 2017). "Increased RAGE and decreased LRP1 immunoreactivity within the microvasculature have been found in Alzheimer's disease patients." (PMID 27563375, 2016).
Alzheimer disease (continued). "The LRP1 protein is involved in the RNA degradation process (hsa03018) and two diseases: Malaria (hsa05144) and Alzheimer's disease (hsa05010)." (PMID 24484584, 2014). "Up-regulation of LRP-1 has been reported in numerous human diseases including Alzheimer disease, breast cancer, prostate cancer, multiple sclerosis, proliferative retinopathy, and ischemic cardiomyopathy." (PMID 25514242, 2014). "Increasing evidence indicates that LRP1 is involved in the pathogenesis of Alzheimer's disease (AD), which is the most common form of dementia." (PMID 25500815, 2014). "Using a mouse model of Alzheimer's disease, the authors demonstrated that boosting the capacity of the sink by administering a form of soluble LRP1, reduces brain amyloid plaque load and improves learning and memory." (PMID 22934024, 2012). "Defects in the low density lipoprotein receptor-related protein-1 (LRP-1) and p-glycoprotein (Pgp) clearance of amyloid beta (Aβ) from brain are thought to contribute to Alzheimer’s disease (AD)." (PMID 22747709, 2012). "In Alzheimer’s disease (AD), a groundbreaking study in a mouse model found that an Ashwagandha root extract induced a liver protein (lipoprotein receptor-related protein 1, or LRP1) that facilitated the clearance of amyloid-beta (Aβ) from the brain." (PMID 40921883, 2025). "So, LRP1 may be a central modulator of Aβ dynamics and a clinically actionable target for treatment of Alzheimer’s disease." (PMID 41582996, 2025). "Understanding the mechanisms through which LRP1 functions, as well as the factors that influence its activity is essential for enhancing Aβ clearance from the brain and developing targeted therapeutic strategies for Alzheimer’s disease." (PMID 41582996, 2025). "Treadmill exercise significantly improved learning and memory, reduced Aβ plaques and sAβ1–42 in the brain and blood, and upregulated the expression of NEP, IDE, and LRP-1 in a rat model of Alzheimer’s disease, with statistically significant differences (p < 0.05 to p < 0.001)." (PMID 40161268, 2025). "Thus, RAP, through its interaction with LRP1, is a key protein in brain cholesterol homeostasis and in the pathophysiology of amyloid β deposition in Alzheimer’s disease (AD)." (PMID 36964401, 2023). "For example, CRISPR/Cas9 made it possible to establish that LRP1 is one of the main proteins responsible for the capture and distribution of the misfolded tau protein within the brain, and to consider neural LRP1 as a potential target for the pathogenetic therapies for Alzheimer’s disease." (PMID 36291103, 2022). "Collectively, these data revealed that syndapin-2 levels are affected in healthy ageing and Alzheimer’s disease, which then may trigger LRP1/Aβ trafficking through the vesicular endosomal pathway." (PMID 35233527, 2022). "Interestingly, LRP1 levels are significantly reduced in brains of patients with Alzheimer's disease." (PMID 35150738, 2022). "LRP1 is known as a causal gene for autosomal recessive keratosis pilaris atrophicans, and association with Alzheimer disease has been reported; however, LRP1 has not been implicated in any skeletal diseases (OMIM 107770)." (PMID 36067312, 2022). "The understanding of the mechanisms and the further identification of LRP1 partners may open up new ways to treat metabolic diseases, such as lipid metabolism, atherosclerosis, inflammation, Alzheimer's disease and obesity." (PMID 34124208, 2021). "This study aims to investigate the mechanisms by which apolipoprotein E (APOE) genotype modulates the relationship between low‐density lipoprotein receptor‐related protein 1 (LRP1) rs1799986 variant on the default mode network (DMN) and cognition in Alzheimer's disease (AD) spectrum populations." (PMID 34387022, 2021). "CSF samples from patients with Alzheimer’s disease demonstrated reduced LRP1 and LRP2-bound Aβ, which may contribute to the elevated brain Aβ in Alzheimer’s disease." (PMID 33066423, 2020).